LINC02937 (long independently transcribed non-coding RNA 2937)
Synonyms: LOC105379829
Gene: Long non-coding RNA gene on chromosome 9 (90,927,338 to 91,213,102, reverse strand). Ensembl gene ENSG00000230537.
Gene Ontology:
Biological process: miRNA-mediated post-transcriptional gene silencing